MGMT (O-6-methylguanine-DNA methyltransferase)
Diseases named in the same sentence as MGMT in open-access papers (continued):
Sharing a sentence is not in itself a finding about the gene and the disease.
glioblastoma (continued). "Although epigenetic inactivation of MGMT is present in approximately 40% of newly diagnosed glioblastoma, the remaining tumours have normal or even elevated levels of MGMT and are resistant to treatment with temozolomide." (PMID 20628383, 2010). "MGMT hypermethylation has been clearly identified as a predictive marker for the response of glioblastomas to alkylating chemotherapy with nitrosourea, temozolomide, or a combination of both." (PMID 19333441, 2009). "Epigenetic silencing of MGMT by means of promoter hypermethylation is present in about 40% of primary glioblastomas and has been identified as the main mechanism reducing MGMT expression and thereby diminishing its DNA repair activity." (PMID 19333441, 2009). "In this regard, the undisputably most important molecular alterations are hypermethylation of the MGMT gene in glioblastomas (Breakout Box 1) and combined deletions of chromosome arms 1p and 19q in oligodendrogliomas (Breakout Box 2)." (PMID 19333441, 2009). "We also obtain 22 glioblastoma samples, a subset of them showing MGMT promoter methylation, as well as three normal brain samples for use as healthy tissue controls." (PMID 19804638, 2009). "In this study, we investigated MGMT promoter methylation in glioblastomas treated with temozolomide and radiotherapy in a single UK treatment centre." (PMID 19536096, 2009). "In MGMT-positive glioblastomas, depletion of MGMT by the addition of O6-benzylguanine significantly enhances the antitumor effect of concurrent radiation + temozolomide." (PMID 19384285, 2009). "On the basis of the MSP assay and bisulphite sequencing some studies have claimed homogeneity in MGMT status within glioblastomas, whereas others have reported a degree of intratumoral heterogeneity." (PMID 19536096, 2009). "Several recent observations suggest that resistance of glioblastomas to alkylating agents seems to follow a more complex pattern than simple dependence on MGMT levels." (PMID 17342095, 2007). "In conclusion, we suggest that application of temozolomide represents a feasible strategy for glioblastoma treatment especially in patients with methylated MGMT promoter even at repeated recurrence and following chemo- and/or RT." (PMID 17342095, 2007). "Alternatively, this can also be explained by low levels of MGMT protein in glioblastoma cells as a consequence of promoter silencing observed in glioblastoma cells." (PMID 12569392, 2003). "Although the methylation of the MGMT promoter has been identified as a predictor for glioblastoma patient survival in numerous studies, there may also be certain limitations." (PMID 40527506, 2026). "Furthermore, we found that SL promotes ubiquitination and degradation of MGMT, consequently enhancing the chemosensitivity of glioblastoma to temozolomide." (PMID 42157950, 2026). "Research conducted by the TCGA has suggested that the predictive value of the MGMT promoter methylation may be confined to glioblastomas of the classical subtype." (PMID 40527506, 2026). "Importantly, as patients with unmethylated MGMT have diminished response to standard-of-care temozolomide therapy, this has been an important factor for inclusion in clinical trials for glioblastoma." (PMID 39796751, 2025). "For instance, glioblastomas with an inactivating hypermethylation of the promoter of the MGMT gene (O6-methylguanine-DNA methyltransferase) exhibit defective DNA repair in response to alkylation and are therefore sensitive to alkylating chemotherapy agents such as temozolomide." (PMID 39066464, 2025). "In non-TCGA patients with glioblastoma, receipt of chemotherapy (HR: 0.20), methylated MGMT (HR: 0.42), 21q loss (HR: 0.54), 19q gain (HR: 0.72), and RB1 alteration (HR: 0.77) positively affected survival." (PMID 39164213, 2025). "Consequently, the LB-100-induced decrease in HIF-1α mRNA expression was followed by reduced MGMT gene transcription in MDR glioblastoma cells." (PMID 40006556, 2025).
glioblastoma (continued). "A deeper understanding of this interplay could inform personalized treatment strategies, integrating MGMT status with immunotherapeutic approaches to improve outcomes in glioblastoma and other refractory cancers." (PMID 40895460, 2025). "Five of the six glioblastoma patients were MGMT promoter methylated." (PMID 40002479, 2025). "Interestingly, when we analysed MGMT gene expression, extrapolated from an available dataset (GEO data repository), in a cohort of primitive and recurrent glioblastomas, we found a significant increase in MGMT expression in recurrent glioblastomas." (PMID 40640872, 2025). "Limited efficacy in MGMT unmethylated glioblastoma patients." (PMID 40014265, 2025). "The observed effects on HIF-1α and MGMT gene expression suggest that LB-100 may enhance the efficacy of approved therapies like temozolomide, commonly used for glioblastoma therapy." (PMID 40006556, 2025). "Glioblastoma is an aggressive brain cancer with poor survival rates, particularly in patients whose tumors lack a specific genetic marker (chemically modified or methylated O-6-methylguanine-DNA methyltransferase [MGMT])." (PMID 41149461, 2025). "The DNA repair protein, O6 methylguanine-DNA methyltransferase (MGMT), directly inhibits the cytotoxic effect of temozolomide, and therefore patients with glioblastoma containing MGMT promoter methylation display better overall survival than those with functional and higher expression of MGMT." (PMID 40072074, 2025). "MGMT promoter methylation is an important biomarker in the management of glioblastoma." (PMID 40725425, 2025). "Temozolomide, the current standard-of-care chemotherapy for glioblastoma, is one such DNA alkylating agent, and it was suspected that MGMT dysfunction may improve therapeutic efficacy." (PMID 39796751, 2025). "In select cases of elderly or poor-performance-status patients with MGMT-methylated glioblastoma, TMZ monotherapy has demonstrated comparable efficacy to radiotherapy, offering a tolerable and effective alternative when radiation is contraindicated or declined." (PMID 41346390, 2025). "Indeed, a decrease in MGMT methylation is often observed in cell lines chronically treated with TMZ as well as in recurrent glioblastomas." (PMID 40640872, 2025). "Such IVD tests are already available for colon (Cologuard® stool-DNA-based test; Epi proColon® 2.0 test; EarlyTect® CRC assay), cervical (Cervi-M® assay), lung (Epi proLung BL Reflex Assay®), glioblastoma (Therascreen MGMT Pyro Kit), bladder (Bladder EpiCheck®) and other tumours (Refs 94, 95)." (PMID 40524349, 2025). "MGMT methylation is observed in 34–45% of glioblastoma cases." (PMID 39941808, 2025). "Currently, there is an ongoing open-label, multi-center, phase 1 study (ClinicalTrials.gov ID NCT05432375) of TINO, used as an adjuvant treatment in patients with newly diagnosed glioblastoma who are MGMT unmethylated and have completed concomitant treatment with TMZ and radiation." (PMID 39859375, 2025). "Similarly, glioblastoma patients with a methylated MGMT promoter, which indicates higher sensitivity to temozolomide, often experience improved survival compared to those without this marker." (PMID 39796773, 2025). "A balanced multicentric control cohort of newly diagnosed MGMT promoter methylated glioblastoma patients, uniformly treated under real‐life conditions with maximum‐safe surgical resection, radiotherapy, and temozolomide according to the EORTC‐NCIC‐26981‐22981/CE.3 trial served as a comparison." (PMID 40260649, 2025). "Importantly, MGMT promoter methylation serves as a clinically significant predictive biomarker in the treatment planning of elderly glioblastoma patients, guiding therapeutic decisions and predicting response to TMZ-based therapy." (PMID 41346390, 2025).
glioblastoma (continued). "According to data from a randomized phase 3 trial involving 573 patients with newly diagnosed glioblastoma who received radiotherapy alone or with concomitant and adjuvant temozolomide, MGMT promoter methylation is a strong predictor of benefit from temozolomide chemotherapy." (PMID 40277764, 2025). "However, a reanalysis of the CE.6 and the pooled Nordic/NOA-08 trials suggests no benefit from temozolomide treatment for older (>60 years old) patients with glioblastoma with truly unmethylated MGMT promoter." (PMID 40277764, 2025). "Interestingly, while MGMT activity can help predict the sensitivity of glioblastoma to temozolomide chemotherapy, current assays are imperfect." (PMID 39796751, 2025). "This study presents the first in-vivo prospective evidence that HSI might be able to predict MGMT promoter methylation status in glioblastoma during surgery with high accuracy." (PMID 41247617, 2025). "Postoperative assessments confirmed IDH wildtype glioblastoma, with unmethylated MGMT promoter." (PMID 40295665, 2025). "The main prognostic factors for glioblastoma (GBM) are age, performance status, histologic grade, and the presence of specific molecular markers, such as MGMT methylation, IDH1/2 mutations, 1p19q codeletion, and EGFR overexpression, according to a new classification." (PMID 40723205, 2025). "Targeting these miRNAs or their interaction with MGMT mRNA may open new therapeutic avenues for overcoming drug resistance, particularly in glioblastoma and colorectal cancer, where MGMT activity critically determines treatment outcome." (PMID 40895460, 2025). "MGMT promoter methylation is detected in approximately 35–45% of glioblastomas." (PMID 40282990, 2025). "Previously, multivariate analyses revealed that patients with IDH1-mutant glioblastoma, now classified as grade 4 astrocytoma, and MGMT promoter methylation exhibited improved survival compared with patients having one or neither of these molecular alterations." (PMID 41149461, 2025). "The weak promoter could be completely repressed by the dispersed methylated CpG, and the transcription stopped completely, which was why many studies have suggested that patients with MGMT promoter methylation have better efficacy with TMZ in glioblastoma." (PMID 39873425, 2025). "Consequently, glioblastoma patients with a methylated MGMT promoter are more responsive to alkylating chemotherapy, resulting in significantly better treatment outcomes and survival." (PMID 41295120, 2025). "Moreover, studies have indicated that unmethylated MGMT glioblastoma tends to exhibit higher ATP values than WHO IV glioma or glioblastoma with methylated MGMT." (PMID 39796751, 2025). "A 2025 proof-of-concept case report described the neoadjuvant administration of a triplet immune checkpoint blockade (nivolumab, ipilimumab, and relatlimab targeting PD-1, CTLA-4, and LAG-3, respectively) in a single patient with newly diagnosed IDH-wildtype, MGMT-unmethylated glioblastoma." (PMID 41511341, 2025). "While MGMT epimutations are frequent in colon cancer, glioblastoma, and B-cell lymphoma, it remains unknown whether constitutional MGMT epimutations are associated with risk of any of these malignancies." (PMID 39980037, 2025). "Further efforts to improve chemotherapy efficacy include the addition of Lomustine to TMZ in patients with MGMT-methylated glioblastoma, resulting in median survival benefits of 48.1 months versus 31.4 months in a recent phase III clinical trial, albeit with increased toxicity." (PMID 41346390, 2025). "Patients with recently diagnosed de novo glioblastoma following completion of chemoradiotherapy were randomized 2:1 to ipilimumab + temozolomide (Arm A) vs temozolomide alone (Arm B), stratified to extent of surgery and MGMT promotor methylation." (PMID 40800123, 2025). "We observed MGMT gene promoter hypermethylation in 40% of glioblastomas using MS-MLPA." (PMID 41567539, 2025).
glioblastoma (continued). "Although chemotherapy may offer some benefits in the management of recurrent glioblastoma, its efficacy appears to be contingent on various factors, including the specific agents used, MGMT methylation status, and the context of other treatments." (PMID 40277764, 2025). "Similarly, MGMT promoter methylation continues to be a potent predictive biomarker for glioblastoma response to temozolomide, impacting the choice of frontline treatment (Bronkhorst and Holdenrieder)." (PMID 41311621, 2025). "Yet, the outcome association was not restricted to patients with MGMT promoter-methylated glioblastoma, indicating that PPIs do not simply decrease the availability or efficacy of temozolomide." (PMID 41288972, 2025). "Moreover, the Phase 1 clinical trial (NCT04842513) is recruiting participants for an immunomodulating multi-peptide vaccine using Pam3Cys-GDPKHPKSF (XS15) for patients with newly diagnosed MGMT-methylated glioblastoma who are HLA-A2-positive." (PMID 40514725, 2025). "Indeed, five of the six patients with a glioblastoma in our study harbored MGMT promoter methylation (patients #1, #2, #3, #4 and #6), further emphasizing the clinical importance of determining MGMT promoter status as a prognostic indicator in neurooncology." (PMID 40002479, 2025). "Epigenetically defined glioblastoma or medulloblastoma subtypes may respond differently to targeted or immune therapies, just as MGMT promoter methylation predicts temozolomide response." (PMID 41487568, 2025). "MGMT methylation is recommended both for glioblastoma and diffuse hemispheric glioma assessment." (PMID 38326661, 2024). "The methylation status of the MGMT promoter is currently the most important prognostic factor and clinically relevant predictor of benefit from temozolomide chemotherapy in patients with newly diagnosed glioblastoma." (PMID 39049072, 2024). "Additional miRNAs with prognostic value include miR‐181d, which represses the MGMT gene, hence functioning as a predictive biomarker of poor survival for glioblastoma patients upon TMZ treatment and miR‐182, which is associated with TMZ susceptibility and a more favourable prognosis." (PMID 39148319, 2024). "Notably, patients with glioblastoma from lower socioeconomic backgrounds are less frequently tested for O6-Methylguanine-DNA-methyltransferase (MGMT)." (PMID 39518322, 2024). "Recent studies have already addressed the dynamic of MGMT methylation in glioblastoma progression." (PMID 39335591, 2024). "Indeed, machine learning and deep learning approaches have gained significant attention in recent years for predicting MGMT promoter methylation status in glioblastoma." (PMID 38385046, 2024). "The effect of DIAPH3 was prominent in MGMT-methylated glioblastoma." (PMID 38454929, 2024). "Prognostic factors, including age, tumor size, feasibility of achieving complete tumor removal, O6-methylguanine-DNA methyltransferase (MGMT) methylation status, and particularly IDH mutation (more prevalent in secondary glioblastomas), markedly influence patient prognosis." (PMID 39330000, 2024). "Therefore, the methylation of the MGMT promoter enhances sensitivity to alkylating agents such as temozolomide and prolonged OS and PFS in comparison to unmethylated MGMT glioblastoma, a rationale for its use as a biomarker in glioblastoma." (PMID 39518074, 2024). "Therefore, MGMT promoter methylation status is a critical prognostic and predictive marker in glioblastoma." (PMID 38167551, 2024). "Additionally, MGMT promotor methylation is more common in the primary site of glioblastoma than in ENM." (PMID 39823071, 2024).
glioblastoma (continued). "Therefore, MGMT promoter methylation level serves as a crucial indicator of the effectiveness of alkylating agents in controlling glioblastoma cells." (PMID 39716317, 2024). "•PRIDE trial aims to improve survival of MGMT-non methylated glioblastoma patients." (PMID 38765202, 2024). "Indeed, in glioblastoma patients, MGMT promoter hypermethylation is an established predictive biomarker for TMZ response and is approved for use in this cancer type." (PMID 39594133, 2024). "While others have described a dose-dependent effect of pharmacologic MGMT inhibition on radiosensitivity, the prevailing consensus does not support a significant influence of MGMT promoter region methylation on the response to radiotherapy in glioblastoma." (PMID 38357209, 2024). "The methylation status of the promoter of the gene that codes for the MGMT protein was searched by polymerase chain reaction (PCR) in 18 patients, finding methylation in 3/10 glioblastomas (30%), 2/3 anaplastic astrocytoma (66%), and 4/4 tumors of the oligodendroglial lineage (100%)." (PMID 39767683, 2024). "Another critical parameter considered to influence the efficacy of combined radiation therapy and temozolomide is the methylation status of the MGMT promoter, which has been shown to be the only molecular feature having both prognostic and predictive values in glioblastoma patients." (PMID 39684714, 2024). "Additionally, patients with glioblastomas showing low MMP-9 expression were generally younger and had higher rates of MGMT promoter methylation and IDH1 mutations compared to patients with glioblastomas with high MMP-9 expression." (PMID 39684754, 2024). "Overall, MGMT methylation was seen in 35% (n = 8), IDH mutations were observed in 35% (n = 8, all grade III), and EGFR amplification was seen in 44% (n = 10, all glioblastoma) of patients, consistent with the heterogenous population of malignant glioma patients." (PMID 38719809, 2024). "Furthermore, MGMT promoter methylation has now been shown to act as a predictive marker for response to TMZ in newly diagnosed glioblastoma." (PMID 39367282, 2024). "In conclusion, MGMT promoter methylation percentage positively correlated with cortical glioblastoma location, while no specific anatomical regions were associated with MGMT methylation status." (PMID 39713243, 2024). "The phenomenon where glioblastomas with an unmethylated MGMT promoter are twice as likely to exhibit disease progression during the course of radiation therapy underscores the significance of MGMT promoter methylation." (PMID 39055560, 2024). "While identifying the crucial marker MGMT for temozolomide (TMZ) resistance in glioblastoma patients presents challenges, AI-based radiomic methods emerge as predictors of both MGMT status and TMZ response, providing valuable insights for informed treatment decisions." (PMID 38553633, 2024). "Establishing relevant prediction models based on the MR image features of the primary tumor using radiomics or machine learning methods have been recognized by numerous studies as an effective method for assessing the MGMT promotor methylation status in glioblastoma patients." (PMID 39716317, 2024). "Its primary objective is to enhance median overall survival (OS), compared to historical median OS rates, in patients with methylguanine methlyltransferase (MGMT) promotor unmethylated glioblastoma by incorporating isotoxic dose escalation to 75 Gy in 30 fractions." (PMID 38116137, 2024). "This study identifies MGMT promoter methylation in a subset of glioblastomas IDH-wild-type." (PMID 40093343, 2024). "Studies have also shown lower O-6-Methylguanine-DNA Methyltransferase (MGMT) expression and MGMT promoter methylation to be associated with improved response to temozolomide-based chemotherapy in PNETs, similar to the utility of MGMT status in glioblastoma." (PMID 39272851, 2024).